ACSS2 (acyl-CoA synthetase short chain family member 2)
Diseases named in the same sentence as ACSS2 in open-access papers (continued):
Sharing a sentence is not in itself a finding about the gene and the disease.
cancer (continued). "Cancer cells can also oxidize and maintain an intracellular pool of acetate by upregulating acetyl-CoA synthetase 2 (ACSS2) in the tricarboxylic acid (TCA) cycle, which converts acetate into acetyl-CoA." (PMID 35513201, 2022). "Compared with the ACLY inhibitors, the researches of ACC inhibitors and ACSS2 inhibitor in cancers need to be increased." (PMID 39086974, 2022). "Through an assay of radiolabeled acetate uptake, a study showed that acetate uptake was increased in cancer cells compared with normal cells, and ACSS2 was found to be involved in the process of acetyl-CoA synthesis from acetate." (PMID 35798917, 2022). "Another promising target for cancer therapy is ACSS2, the enzyme responsible for capturing acetate, the major source of acetyl-CoA, especially in hypoxia." (PMID 35887244, 2022). "In conclusion, ACSS2 mediates the reversible conversion of acetyl-CoA and acetate in cancer cells, which is key to understanding the survival of cancer cells." (PMID 35798917, 2022). "Under hypoxic circumstances, ACSS2 can shift metabolism of cancer cells from aerobic glycolysis to oxidative phosphorylation (OXPHOS)." (PMID 36010906, 2022). "Studies have proven that ACSS2 inhibitors can be effective in halting cancer growth and can be combined with other antineoplastic drugs to reduce drug resistance." (PMID 35740562, 2022). "In vitro experiments on a variety of cancer cells have shown that ACSS2 expression determines the uptake and utilization of acetate." (PMID 35740562, 2022). "For example, the production of ACLY-dependent acetyl-CoA was recently found to play an important role in the early stage of pancreatic cancer development, and once cancer is formed, ACSS2 is highly expressed." (PMID 39086974, 2022). "ACSS2 is an enzyme that contributes to histone acetylation and lipogenesis in cancer cells, especially under stress conditions such as hypoxia or glucose deprivation." (PMID 36439127, 2022). "MTB-9655, a small-molecule inhibitor of ACSS2, is a potential therapeutic agent for cancer patients and has entered a phase I (dose escalation) clinical trial (NCT04990739)." (PMID 35798917, 2022). "Essentially, lipid synthesis by ACSS2 in the acetate pathway has been shown to support cancer cell survival under metabolic stress, suggesting an essential role of lipids in cancer cell adaptation to harsh environments." (PMID 36551752, 2022). "In low-oxygen and lipid-depleted conditions, ACSS-2 overexpression contributes to cancer cell growth." (PMID 36578540, 2022). "Inhibitors of ACSS2 have been developed, such as novel substituted tetrazoles and amide-substituted condensed pyridine derivatives for the treatment of cancer." (PMID 35740562, 2022). "The abnormal expression of ACSS2 has also been observed in several cancers, making it a potential target for cancer therapy." (PMID 36555470, 2022). "Analysis of the cBioPortal, GEPIA2, UALCAN, and TCGA databases showed that ACSS2 transcript levels were significantly upregulated in multiple cancer types including CESC." (PMID 34206705, 2021). "We used seven algorithms to quantify the density of CD8+ T cells in each cancer type and then correlate it with ACSS2 expression levels." (PMID 34206705, 2021). "ACSS2 and its role in cancer has been extensively studied, with expression levels found to correlate with tumor aggressiveness." (PMID 33946927, 2021). "Cancer cells exhibited activated cytosolic ACSS2-mediated acetate metabolism, which promotes tumor growth by replenishing the acetyl-CoA pool under hypoxia, acidosis and other stressed conditions." (PMID 34888248, 2021). "Whereas in cancer cell lines acetate is converted to acetyl-CoA by the action of cytosolic ACSS2, this enzyme was dispensable for acetyl-CoA generation in acetate-treated memory T cells." (PMID 33679780, 2021).
cancer (continued). "The overexpression of ACSS2 was observed in diverse cancers including glioblastoma and brain metastases, hepatocellular carcinoma, and breast and colorectal cancers and correlated with tumor progression both in humans and in murine models." (PMID 32575796, 2020). "In part 2 of this review, we will focus on the roles of acetate and ACSS2 in various disease states, including cancer." (PMID 33281616, 2020). "In these metabolically stressed conditions, the upregulated expression of ACSS2 was responsible for cancer cell growth and survival by increasing lipid biomass." (PMID 32575796, 2020). "Studies on acetate utilization via ACSS2 in cancer have shown that acetate is released by cancer cells under hypoxic conditions, and that inhibition of ACSS2 reduces acetate production and release." (PMID 33304273, 2020). "It is in these two roles of facilitating histone and transcription factor acetylation that ACSS2 can affect metabolic reprograming and cell cycle progression in cancer cells through epigenetic means." (PMID 33304273, 2020). "In this same context, ACSS2 can reprogram cancer cells to adapt to nutrient deprivation and other stressors, such as hypoxia." (PMID 33304273, 2020). "The authors proposed that ACSS2 in cancer cells is capable of running the reverse reaction and generating acetate from existing acetyl-CoA." (PMID 33304273, 2020). "More recent studies have shown that in cancer cells, ACSS2 is expressed in cell nuclei, where it operates to recycle acetate derived from HDAC-mediated deacetylation reactions during hypoxia." (PMID 33304273, 2020). "In order to better understand the roles of ACSS2 in cancer, it is helpful to compare its function to that of ATP-citrate lyase (ACLY)." (PMID 33304273, 2020). "A functional genomics study showed that the activity of ACSS2 contributes to cancer cell proliferation under lipid deprivation conditions." (PMID 32252351, 2020). "ACSS2 expression is up-regulated during metabolic stress and correlates with cancer progression and metastasis." (PMID 32252351, 2020). "Even in the case of lipogenesis, acetate acts as an epigenetic regulator of lipid synthesis via ACSS2 under hypoxic conditions in cancer cells derived from hepatocytes." (PMID 33304273, 2020). "There is a similar or opposite trend for key gene expression, ACSS2 is decreased in 5 cancers, and ALCY is found in 5 tumors compared to their normal samples." (PMID 31828117, 2019). "ACSS2 metabolism has been shown to be a critical gene for cancer cell survival under conditions of metabolic stress, as it facilitates the use of acetate as a nutritional source." (PMID 29796188, 2018). "ACSS2 contributes to histone acetylation in cancer cells, especially under hypoxia or glucose deprivation, and can also participate in recycling of acetate released from histones by the action of histone deacetylases." (PMID 30568658, 2018). "Exogenous acetate augments Acss2/HIF-2 dependent cancer growth and metastasis in cell culture and mouse models." (PMID 29281714, 2017). "Consistent with its earlier reported role as a biochemical flare, acetate increases in hypoxic cancer cells and induces hyper-acetylation of histone 3 in a partially Acss2-dependent manner." (PMID 29281714, 2017). "In the absence of ACLY, under nutrient deprivation or stress conditions, cells upregulate ACSS2, enabling cancer cells to utilize acetate to sustain tumor growth by providing acetyl CoA for fatty acid and phospholipid synthesis and histone acetylation." (PMID 29354634, 2017). "Since knockout or siRNA knockdown of Acss2 inhibits cancer cell proliferation, direct evidence that ACSS2-specific inhibitors blocks cancer cell development in vitro and in vivo, is expected." (PMID 29295482, 2017). "Here we apply innovative stable isotope tracing and mass spectrometry approaches to quantify acetate consumption and utilization by downstream pathways in a panel of cancer cell lines with varying levels of ACSS2 expression." (PMID 28099844, 2017).
cancer (continued). "The higher percentage of ACSS1 high-expression cases than that of ACSS2 fully proves the importance of ACSS1 in acetate utilization by cancer." (PMID 27357947, 2016). "Acetate release from cancer cells increases during prolonged hypoxia and depletion of ACSS2 affects lipid composition." (PMID 25689462, 2015). "In contrast, ACSS2 expression was reduced in cancer tissues relative to normal tissues." (PMID 41544165, 2026). "Notably, ACSS2 is found in the nucleus of certain cancer cells, where it maintains histone acetylation under hypoxic and nutrient‐limited conditions by recapturing acetate released during deacetylation." (PMID 40060193, 2025). "ACSS2 expression is increased in cancer cells that are under metabolic stress." (PMID 40381373, 2025). "In addition, under conditions of metabolic stress such as hypoxia or lipid depletion, cancer cells upregulate acetyl-CoA synthetase 2 (ACSS2) to generate acetyl-CoA from acetate." (PMID 40723225, 2025). "As expected, ACSS2 inhibition abrogated acetate-mediated survival of cancer cells under acidosis." (PMID 38429478, 2024). "The findings suggest that therapeutic strategies aimed at modulating acetate levels or targeting the enzymes involved in acetate metabolism, such as ACSS2, could significantly improve T cell responses and overall efficacy in cancer immunotherapy." (PMID 39351241, 2024). "We detected in PR elevated levels of enzymes (COX-2, ACSS2, FDPS, FASN, ACAT2, ACLY, SLC12A2) and metabolites (arachidonic acid and carnitine) involved in lipid metabolism, which have been linked to radioresistance of cancer cells." (PMID 38410100, 2024). "In addition, patients with cancer recurrence and/or progression had lower ACSS2 levels than did those who achieved disease-free status." (PMID 38528124, 2024). "We next tested whether ACSS2 is critical for acetate-induced cancer cell survival under low-pH conditions." (PMID 38429478, 2024). "Furthermore, hypoxic cancer cells can also use acetate via acetyl-CoA synthetase 2 (ACSS2) to generate acetyl-CoA21,22." (PMID 39251875, 2024). "As ACLY and ACSS2 have also been found to provide substrates for histone acetylation, modulation of acetyl-CoA metabolism can also affect gene expression programmes in cancer cells." (PMID 39251875, 2024). "Despite prominent studies suggesting that acetate usage is limited to nutrient-depleted or hypoxic conditions and links between high ACSS2/acetate usage and enhanced cancer malignancy, such generalizations may require caution." (PMID 38528124, 2024). "In addition, ACSS2 was shown to mediate the reprogramming of the synthesis and utilization of fatty acids in a way that supports the tumorigenic properties of cancer cells." (PMID 38515158, 2024). "Furthermore, the treatment of cancer cells with ACSS2 inhibitor under acidosis reduced the flux of 14C-acetate into the total histone proteins in multiple PDAC cell lines." (PMID 38429478, 2024). "Also, ACSS1 and ACSS2 expression levels can affect the net acetate uptake rates in several cancer types." (PMID 38851813, 2024). "However, this same and other mutant Acss2 proteins are extremely unstable when expressed endogenously in mice and exhibit lower levels even when over-expressed in cancer cell lines." (PMID 36862715, 2023). "In addition, siRNA transfection significantly inhibited ACSS2, resulting in decreased proliferation of cancer cells under nutritional stress, suggesting that acetate utilization by ACSS2 is a crucial factor in these cells." (PMID 35798917, 2022). "Furthermore, ACSS2-mediated acetate uptake is related to de novo synthesis of fatty acids in cancer cells." (PMID 35798917, 2022). "ACSS2 expression is upregulated in hypoxic states, and inhibition of ACSS2 in cancer cells during chronic hypoxia enhances cell death, suggesting that ACSS2 might function as a crucial factor in the survival of cancer cells under hypoxic conditions." (PMID 35798917, 2022).
cancer (continued). "On the contrary, there are few studies on the use of an ACSS2 inhibitor to block cancer growth." (PMID 39086974, 2022). "In addition, ACSS2 plays an important role in synthesis of acetyl-CoA and inhibition of ACSS2 produces anti-cancer effects." (PMID 39086974, 2022). "In addition, tetrazole and novel amide-substituted condensed pyridine derivatives have recently applied for cancer treatment as two new ACSS2 inhibitors." (PMID 39086974, 2022). "However, increased rates of metastasis and poor prognosis in some cancer patients correlated with downregulation of ACSS2 expression." (PMID 35887244, 2022). "Cells are more dependent on acetate metabolism when metabolically stressed, including hypoxia and/or nutrients, which may explain increased ACSS2 expression in cancer." (PMID 33937302, 2021). "Further, ACSS2 was upregulated in the cancer cells and inhibition of ACSS2 via siRNA greatly reduced cancer cell proliferation under nutrient stress, indicating the importance for acetate utilization through ACSS2 in these cells." (PMID 33304273, 2020). "Similarly, in cancer cells exposed to glucose or oxygen deprivation, there is an increase in intracellular acetate levels and translocation of ACSS2 from the cytoplasm to the nucleus." (PMID 33304273, 2020). "Because it has also been described that acetate could profit cancer cells by being a lipogenic substrate under hypoxia mainly through an ACSS2‐dependent mechanism, we verified in our model if ACSS2 expression increased under hypoxia." (PMID 33107196, 2020). "The mitochondrial forms, ACSS1 and ACSS3, most likely play a significant role in energy derivation via oxidation of acetate and propionate, respectively, but may be less involved in regulatory functions in cancer cells than ACSS2." (PMID 33304273, 2020). "Many cancer cells overexpress ACSS2 to utilize environmental acetate as a fuel of biosynthesis." (PMID 32029721, 2020). "Reports on the role of ACSS2 expression in cancer have been controversial." (PMID 31750240, 2019). "Recent studies have shown that metabolic enzymes, such as ketohexokinase (KHK)-A and acetyl-CoA synthetase 2 (ACSS2), are moderated spatially and temporally in cancer cells so that these enzymes not only have changes in metabolic activities but also gain non-canonical functions." (PMID 31750240, 2019). "Acss2-mediated acetyl CoA generation in both the cytosol and nucleus are important in cancer cells." (PMID 29281714, 2017). "The extensive fatty acid labeling from 13C-acetate in hypoxic cancer cells may indicate that the increased ACSS2 expression supports biomass production." (PMID 28099844, 2017). "In cancer cells exposed to oxygen or glucose deprivation, there is an increase in cellular levels of acetate, a substrate for acetate-dependent acetyl CoA synthetase 2 (Acss2) that also stimulates translocation of Acss2 from the cytosol to the nucleus." (PMID 29281714, 2017). "As the major enzymes in acetate metabolism, ACSS1 and ACSS2 may merit further explorations as a therapeutic target for cancer." (PMID 27357947, 2016). "Our finding that exogenous acetate promotes cancer growth and metastases in an animal model via ACSS2 and HIF-2 identifies this pathway as one that potentially may be influenced by environmental cues." (PMID 25689462, 2015). "Therefore, ACSS2 holds promise as a potentially significant target for cancer treatment." (PMID 41300803, 2025). "Notably, ACSS2 is found at elevated levels in numerous cancer types and it is typically upregulated in response to hypoxic conditions and nutrient scarcity which means it may play a crucial role in helping cancer cells endure the stresses of the TME." (PMID 39594997, 2024). "Furthermore, ACSS2 serves a dual function during acidosis by facilitating histone acetylation in cancer cells and enhancing the stability of the transcription factor SP1, which synergize to commence metabolic reprogramming under acidosis through the regulation of SAT1." (PMID 38429478, 2024).
cancer (continued). "Therefore, not surprisingly, the dysregulation of Acss2 has been linked to various human diseases, including cardiovascular diseases, cancer, diabetes, and obesity." (PMID 36835088, 2023). "Furthermore, ACSS2 promotes increased cancer cell survival partially by maintaining autophagy." (PMID 35798917, 2022). "Similarly, ACSS2 induces apoptosis of cancer cells by activating AMPK." (PMID 39086974, 2022). "The authors hypothesize that ACSS2 may act to buffer acetate and acetyl-CoA levels in cancer cells." (PMID 33304273, 2020). "However, whether ACSS2 pS659 expression is a biomarker for the clinical features and prognosis of cancer is unknown." (PMID 31750240, 2019). "Given the important role of ACSS2 as a central node between metabolism and epigenetic regulation in cancer, it is tempting to speculate that the cholesterol levels in cancer cells may have an impact on gene regulation through the modulation of ACSS2 enzymatic activity." (PMID 29354634, 2017). "Furthermore, it would explain recent findings on the importance of ACSS2 in cancer cells." (PMID 27110360, 2016). "A second class of ACSS2 inhibitors, MTB-9655 has also become commercially available and is currently in clinical trials for cancer therapy." (PMID 39801522, 2025). "Enzymes such as ACLY, ACSS2, and ACC1 are widely upregulated in various cancers, including CRC, underscoring their critical roles in the metabolic hub centered on acetyl‐CoA." (PMID 40060193, 2025). "Additionally, ACSS2 null mice are phenotypically normal, without embryonical or developmental deficiencies, suggesting that ACSS2 may be a non-essential gene under normal conditions, making ACSS2 an attractive cancer-specific target." (PMID 38818373, 2024). "Here we tested the effects of ACSS2 on HIF-2α and cancer cell metabolism and growth in ccRCC models and clinical samples." (PMID 38941296, 2024). "Moreover, the compelling evidence on the role of ACSS2 in regulating the acetate levels through nuclear histone acetylation, fatty acids biosynthesis, and recycling of acyl groups when glucose or oxygen is deprived in cancer led us to further explore the role of ACSS2 in AML." (PMID 38851813, 2024). "Our current and previous studies indicate that Acss2 facilitates cancer growth in part via effects on HIF-2 signaling and these Acss2-dependent effects are augmented with supplemental acetate admistration." (PMID 36862715, 2023). "For example, cancer cells were sensitive to oxaliplatin with the elevated expression of MYC, whereas they were insensitive with the increased expression of ACSS2." (PMID 36119478, 2022). "Our analysis showed that ACSS2 expression and CAF abundance were negatively correlated in most of the cancer types." (PMID 34206705, 2021). "AMP-activated protein kinase (AMPK) impacts acetyl-CoA pools and histone acetylation in cancer through phosphorylation of at least two relevant targets: acetyl-CoA carboxylase (ACC1) and ACSS2." (PMID 34109280, 2021). "Several cancer cell lines, particularly under conditions of ACLY deficiency, hypoxia or nutrient limitation, favor this pathway, but even under glucose-replete conditions ACSS2 may be preferably used to support de novo lipogenesis, as in case of human cytomegalovirus infection (HMCV)." (PMID 33679780, 2021). "While one major acetate source providing substrate for ACSS2 is through ubiquitous protein deacetylation reactions, such as histone deacetylation, NAA is another readily available source of acetate in cancer cells that express NAT8L, ASPA, and ACSS2." (PMID 33304273, 2020). "We analyzed the expression of five major DNFA enzymes SCD, FASN, ACLY, ACSS2 and ACACA using RNA-Seq data from 30 diverse cancer types in The Cancer Genome Atlas (TCGA)." (PMID 31316083, 2019). "For example, ACLY, ACSS2, and PDC have been considered as potential molecular targets for anti-cancer therapy due to their functions in nuclear acetyl-CoA production and histone acetylation." (PMID 30283496, 2018).